IL1B (interleukin 1 beta)
Diseases named in the same sentence as IL1B in open-access papers (continued):
Sharing a sentence is not in itself a finding about the gene and the disease.
endotoxemia (continued). "Collectively, these data display that the SEM18 peptide significantly inhibited TNF-α and IL-1β, but not IL-6, in endotoxemia-treated mouse lung tissues." (PMID 35337084, 2022). "Considering the primary role of TNF-α in modulating the expression of IL-1β and IL-6, we hypothesized that TNF-α may have a more immediate role in systemic inflammation and organ injury (e.g., the lungs) in endotoxemia." (PMID 35337084, 2022). "Endotoxemia mortality results exclusively from a systemic inflammatory response characterized by an acute increase in circulating inflammatory cytokine levels (e.g. TNF, IL-6, and IL-1β) from splenocytes and myeloid-derived innate immune cells." (PMID 36264059, 2022). "Interestingly, compared with LPS treatment group, remimazolam remarkably improved survival rate of endotoxemia mice and decreased the release of LPS-induced inflammatory mediators (such as TNF-α, IL-6, and IL-1β)." (PMID 34867346, 2021). "For animals resuscitated with HSA and PolyHSA, serum TNF-α and IL-1β levels were significantly lower at 6 and 24 h after LPS induced endotoxemia compared to animals that received no fluid resuscitation." (PMID 34035380, 2021). "Because IL-18 regulates the synthesis of TNF-α, IL-1β, IL-8 and MIP-1α, removal of IL-18 may have a beneficial effect in lethal endotoxemia in naive mice." (PMID 32503314, 2020). "Deletion of IFN-α/βR, the receptor for type 1 IFN, but not Rip3, significantly inhibited the release of IL-1α and IL-1β in endotoxemia." (PMID 30587103, 2018). "In conclusion, our findings indicate that glibenclamide could ameliorate myocardial injury and reducing IL-1β and TNF-α possibly through inhibiting Nalp3 inflammasomes and Caspase-1 signaling under LPS-induced endotoxemia in STZ diabetic mice." (PMID 25077824, 2014). "Likewise, the slow-releasing H2S donor GYY4137, can reduce LPS-induced endotoxemia in mice, as well as the synthesis of pro-inflammatory mediators (such as TNF-α, IL-1β, IL-6, NO and PGE2) by LPS-stimulated RAW 264.7 macrophages in vitro." (PMID 24237604, 2013). "After detection using ELISA and Western blot assays, it has also been found that propofol can not only promote the expression of Annexin A1, but also inhibit the phosphorylation level of p38 and release of inflammatory factors (IL-1β, IL-6 and TNF-α) in rats with endotoxemia." (PMID 22164217, 2011). "In this model of early endotoxemia, IL-1β production is not yet present in the systemic circulation." (PMID 17397554, 2007). "We assessed the therapeutic efficacy between triple cytokine (tumor necrosis factor-α [TNF-α], interleukin-1β [IL-1β], and IL-6) inhibition (mediated by KCF18 peptide) and single cytokine (TNF-α) inhibition (mediated by SEM18 peptide) on alleviating lung injury in the early phase of endotoxemia." (PMID 35337084, 2022). "Both the accumulation of inflammation cytokines especially IL18 and IL1β, and the activation of NLRP3/ASC/Caspase 1 inflammasome complex in damaged colon indicated that endotoxemia-induced colonic mucosa injury might be related with inflammation-related pyroptosis." (PMID 33679744, 2021). "Thus, systemic reduction in pro-inflammatory cytokines by POP2 favours resistance to endotoxemia, but not to the same extent as IL-1β processing defects." (PMID 28580947, 2017). "Therefore, we hypothesize that sesamol increases IL-10, decreases the production of TNF- and IL-1β to balance the SIR against LPS-induced hypotension and endotoxemia." (PMID 26839527, 2015). "Thus, preservation of Eh Cys/CySS by SAA supplementation may be involved in decreased IL-1β and TNF-α levels during endotoxemia." (PMID 19325908, 2009). "It is possible that in this early model of endotoxemia, IL-1β was not yet produced." (PMID 17397554, 2007). "In early endotoxemia, the more severe lung injury observed in neutropenic compared to non-neutropenic rats does not depend on TNF-α, IL-1β and MIP-2 in the lung." (PMID 17397554, 2007).
endotoxemia (continued). "Most importantly, acute administration of quercetin reduces the lethality rate and circulating levels of TNF-α and IL-1β in C57BL/6J mice with endotoxemia induced by LPS, whereas chronic dietary supplementation with quercetin shows no inhibitory effect on serum TNF-α and IL-1β levels." (PMID 24260470, 2013).
ulcerative colitis (159 papers, 2009 to 2025). An inflammatory bowel disease involving the mucosal surface of the large intestine and rectum. "The damage caused by ulcerative colitis to the mice's colon was significantly reduced, and the relative expression levels of IL‐1β, IL‐6, and TNF‐α were all significantly downregulated." (PMID 40330205, 2025). "Neutrophils also secrete pro-inflammatory cytokines (TNF-α, IL-1β) and chemokines (IL-8—a potent chemotactic factor for neutrophils, whose concentration has been associated with ulcerative colitis endoscopic and histological activity)." (PMID 41010030, 2025). "Serum inflammatory markers such as TNF-α, IL-6 and IL-1β are often considered as hallmark of ulcerative colitis." (PMID 36159798, 2022). "High levels of IL-1β can cause an abnormal intestinal immune response, leading to ulcerative colitis." (PMID 36558551, 2022). "It amplifies inflammation by activating other cells, by upregulating some cytokines (Il-1β and IL-6) and by stimulating NF-κB—an indispensable pathway in ulcerative colitis pathogenesis." (PMID 41010030, 2025). "High-damaging Candida albicans strains tend to form hyphae and exacerbate intestinal inflammation in ulcerative colitis patients through IL-1β-dependent mechanisms." (PMID 39939579, 2025). "IL-1β was previously identified as a decorative component of NETs in patients with inflammatory diseases like active ulcerative colitis and non-alcoholic steatohepatitis." (PMID 40547021, 2025). "This shift reduces pro-inflammatory cytokines (TNF-α, IL-1β, IL-6), elevates anti-inflammatory IL-10, and mitigates mucosal damage, positioning miR-223 as a potent therapeutic candidate for ulcerative colitis (UC)." (PMID 40799643, 2025). "Application of a new ultrasensitive technique of quantifying cytokines in plasma to cohorts of patients with ulcerative colitis showed all cytokines examined, except IL‐13 and IL1β, were readily measurable within the linear concentration range in most samples." (PMID 40584280, 2025). "The classic TCM formulaSi-Wu decoction significantly decreases the levels of IL-6, TNF-α, and IL-1β, effectively treating ulcerative colitis." (PMID 38379418, 2024). "Protein-protein interaction analysis has underscored the significance of hub genes, notably Stat3, Il1b, Mmp3, and Lgals3, in the progression of ulcerative colitis." (PMID 38308210, 2024). "Conversely, pathogenic bacteria like Oscillibacter, which is positively correlated with IL-1β levels and increased in conditions such as ulcerative colitis, exhibited increased abundance on 3rd day of hyperuricemia." (PMID 38088975, 2023). "The NLRP3 inflammasome drives release of pro‐inflammatory cytokines including interleukin (IL)‐1β and IL‐18 and is a potential target for ulcerative colitis (UC)." (PMID 37962000, 2023). "COST reduced the inflammatory response in mice with ulcerative colitis by lowering the proinflammatory cytokines IL-1β, IL-6, and TNF-α." (PMID 37736519, 2023). "We first analyzed the expression levels of GLI1, IL-1A, and IL-1B with the published dataset and found that they were increased in ulcerative colitis compared to health tissues." (PMID 37889976, 2023). "Some inflammatory cytokines associated with ulcerative colitis include tumor necrosis factor alpha (TNF-α) and interleukin-1 beta (IL-1β)." (PMID 38024826, 2023). "1,25(OH)2D3 treatment also inhibited caspase-1 activation and IL1β secretion in an ulcerative colitis model." (PMID 37867510, 2023). "A previous study reported that Oscillibacter was increased in mice with ulcerative colitis (UC) and was significantly positively correlated with IL-6 and IL-1β levels." (PMID 36786568, 2023). "Decreased intracellular Ca2+ stores and increased IL-1β can inhibit smooth muscle cell contraction in ulcerative colitis." (PMID 36501176, 2022).
ulcerative colitis (continued). "From an anti-inflammatory perspective, lycopene was able to reduce the following inflammatory biomarkers: TNF-α, IL-1β, and IL-6 in the acetic acid-induced ulcerative colitis rat model." (PMID 35990343, 2022). "We previously found elevated BAFF in serum, stool and colon tissue of adults with ulcerative colitis and Crohn’s disease, and serum BAFF levels correlated with disease activity, ESR, TNF-α, and IL-1β in ulcerative colitis patients." (PMID 35320937, 2022). "Our study also further confirmed the important role of inflammatory factors, such as NO, TNF-α, IL-1β and IL-6, in the occurrence and development of ulcerative colitis." (PMID 35163182, 2022). "Previous studies in ulcerative colitis have demonstrated that blocking IL-1R2 upregulated the expression of pro-inflammatory chemokines induced by Il-1β, such as TNF-a, IL-6 and IFN-γ." (PMID 35087030, 2022). "It was reported that the levels of IL-1β and Mpo in feces of patients with ulcerative colitis were positively correlated with the severity of the disease." (PMID 34007409, 2021). "TNF-α, IL-1β and IL-6 are the cytokines which play pro-inflammatory roles in the process of ulcerative colitis." (PMID 34604183, 2021). "IL-1β expression was shown to be markedly elevated in colonic tissues of ulcerative colitis patients and directly correlated with an increase in miR-200c-3p expression." (PMID 34759934, 2021). "Baicalin can significantly reduce the serum interleukin-17 (IL-17), IL-6, and IL-1β expression in Ulcerative Colitis (UC) rats." (PMID 34692749, 2021). "Suppression of IL-1β and IL-6 inflammatory markers in macrophages, and dependent-protection against ulcerative colitis." (PMID 33868227, 2021). "Our results indicate that drug delivery formulations significantly increased MFI values for lymphocytes in patients with ulcerative colitis, while the mRNA expression of Tnfa, Il1b, and Il17 was significantly decreased." (PMID 32933548, 2020). "In IBD patients with Crohn’s disease and ulcerative colitis, mucosal mononuclear cells express IL-1β, and a positive correlation between severity and IL-1β expression has been demonstrated." (PMID 32989233, 2020). "The inflammatory cytokines, including TNF-α, IL-1β and IL-6, were also suppressed and the percentages of macrophages were decreased, after using a kind of anti-ulcerative colitis medicine in CAC." (PMID 33201893, 2020). "Patients with ulcerative colitis have higher baseline levels of IL1β and TNF-α than in patients with Crohn’s disease." (PMID 32933548, 2020). "Oscillibacter abundance was considerably positively related to IL-1β and IL-6 expressions and ulcerative colitis pathological scores in mice." (PMID 33178314, 2020). "In particular, fecal levels of IL-6, IL-8 and IL-1β are elevated in the context of acute bacterial or viral gastroenteritis and ulcerative colitis." (PMID 32909002, 2020). "UroA/UAS03 treatment also reduced neutrophil infiltration as evident from myeloperoxidase (MPO) activity as well as serum inflammatory markers such as IL-6, TNF-α, CXCL1, and IL-1β that are hallmarks of ulcerative colitis." (PMID 30626868, 2019). "Studies have shown that levels of the pro-inflammatory cytokines, IL-1β and IL-6, are predictably increased in the mucosa of patients with Crohn's disease and ulcerative colitis." (PMID 31749791, 2019). "Expression of the nuclear receptors RXRα and PPARα was decreased in inflamed colonic-mucosa of ulcerative colitis patients and in IL-1β-treated Caco2-BBE cells." (PMID 28223944, 2017). "Significant decreases were seen in the levels of IFN-γ, IL-1β, and IL-6, all of which are elevated in human lamina propria mononuclear cells isolated from ulcerative colitis and Crohn's disease patients." (PMID 26457007, 2015). "In a murine model of ulcerative colitis, IL-1β pre-treated MSCs were found to exhibit significantly higher therapeutic efficacy than untreated MSCs." (PMID 25266361, 2014).
ulcerative colitis (continued). "Activated macrophages and neutrophils secrete proinflammatory cytokines such as TNF-α, IL-1β, and IL-6 to regulate the inflammatory response in the colonic mucosa of patients with ulcerative colitis." (PMID 24971344, 2014). "It has also been shown that IL-1β and IL-2 production is significantly increased in active ulcerative colitis and is significantly correlated to its activity index." (PMID 23497090, 2013). "Fibroblasts from patients with ulcerative colitis also increased MMP-1 while treatment with imipramine resulted in MMP-1-levels with significant inhibition when compared to cells with IL-1β or TNF only." (PMID 19787068, 2009). "For instance, cecropin A not only effectively reduced the levels of proinflammatory factors TNF-α, IL-6, and IL-1β in the colon tissues of mice with ulcerative colitis but also reduced the E. coli-induced expression of IL-6, IL-8, and TNF-α mRNAs in porcine intestinal epithelial cells (IPEC-J2)." (PMID 41099619, 2025). "Additionally, podophyllotoxin significantly lowered the levels of inflammatory cytokines (TNF-α, IL-1β, IL-6) in the serum and colonic tissues of ulcerative colitis model mice and improved oxidative stress status." (PMID 40432443, 2025). "As a result, this research utilized 11 serotonin derivatives to assess the effect of NO on LPS-stimulated RAW 264.7 cells and its role in regulating crucial cytokines linked to ulcerative colitis, specifically IL-6, TNF-α, IL-1β, and IL-10, through Griess and RT-qPCR assays." (PMID 40649400, 2025). "Glycyrrhiza uralensis alleviated intestinal inflammation by inhibiting pro-inflammatory factors (e.g., IL-6 and IL-1β), and mitigated ulcerative colitis by repairing mitochondrial damage and increasing SOD, GSH-PX, and IL-10 levels in intestinal epithelial cells." (PMID 41180229, 2025). "Pharmacological research shows that a 90% ethanol extract of D. lablab flowers can also significantly suppress the expression of inflammatory cytokines such as IL-6, TNF-α, and IL-1β in a mice model of ulcerative colitis and promote the recovery of intestinal epithelial tight junctions." (PMID 39202831, 2024). "To investigate the effects of DID on the expression of inflammatory factors and intestinal barrier protein in colonic tissues of mice with DSS-induced ulcerative colitis, we detected the expressions of IL-6, IL-1β and TNF-α in DSS-stimulated colon tissues via Western blot." (PMID 39452928, 2024). "As an ingredient in TCM with dual applications in both medicinal treatment and dietary consumption, D. lablab flowers have been reported to significantly suppress the expression of inflammatory cytokines such as IL-6, TNF-α, and IL-1β in a mice model of ulcerative colitis." (PMID 39202831, 2024). "mentioned that Triptolide inhibited the IL-1β expression in an ulcerative colitis mouse model." (PMID 39950099, 2024). "Methods and Results: Our results indicated that didymin could alleviate the symptoms of ulcerative colitis, as it inhibited the expressions of interleukin-6 (IL-6), interleukin-1β (IL-1β) and tumor necrosis factor-α (TNF-α)." (PMID 39452928, 2024). "Additionally, NLRP3 inflammasome has been investigated relatively to having a role in the pathogenesis of ulcerative colitis, as it is responsible for activating the expression of caspase-1, producing IL-1β and IL-18 and starting the inflammatory process." (PMID 35745756, 2022). "Interestingly, the organoids generated from colonic tissue from ulcerative colitis patients also showed marked increase in IL-1β and miR-200c-3p expression compared to the organoids from the healthy control patients." (PMID 34759934, 2021). "Patients with ulcerative colitis have impaired expression of pparγ in the colon and the increased expression of this gene can lead to the inhibition of inflammatory cytokines such as IL-1β and TNF-α." (PMID 34987390, 2021).
ulcerative colitis (continued). "For example, Oscillibacter, which is enriched in mice with ulcerative colitis, is significantly positively correlated with the IL-6 and IL-1β levels, which implies that the gut microbiota might orchestrate immunity by regulating the secretion of cytokines." (PMID 33469451, 2020). "In this study, the pharmacological stimulation of A3AR, via Cl-IB-MECA, decreased TNF and IL-1β production and attenuated NF-κB p65 activation in colonic tissues in patients with ulcerative colitis, thus corroborating the use of A3AR agonists as an efficacious treatment for IBD patients." (PMID 32575844, 2020). "Interestingly, GSK2256294 reduced IL4 and IFNγ in ulcerative colitis, and IL1β in Crohn's disease specifically, suggesting potential differential effects of GSK2256294 in these two diseases." (PMID 31002701, 2019). "In addition, the activity of proinflammatory cytokines such as tumor necrosis factor α (TNF-α), interleukin 1β (IL-1β), and IL-6 is increased in the colonic mucosa of patients with ulcerative colitis." (PMID 24971344, 2014). "Supplementation with a 20% dose of peeled highland barley restored body weight, disease activity index, colon length, serum IL‐1β and IL‐10 levels, liver GSH‐Px content, and SOD activity to normal levels in mice compared to ulcerative colitis mice." (PMID 40330205, 2025). "Astragalus polysaccharide significantly alleviates colonic damage in ulcerative colitis by inhibiting pro-inflammatory factors (TNF-α, IL-6, IL-1β) and oxidative stress products (MDA) and restoring the activity of antioxidant enzymes (SOD)." (PMID 41395463, 2025). "In a related study on a DSS-induced ulcerative colitis (UC) model, inhibition of the mTOR axis significantly reduced the expression of TNF-α, IL-1β, and iNOS, leading to improved conditions." (PMID 40077417, 2025). "In rats with ulcerative colitis, low doses of PC administered orally for one week decreased the expression of TNF-α, IL-1β, and IL-6 and increased the level of transforming growth factor (TGF)-β, which is essential for healing of the intestinal mucosa." (PMID 40498951, 2025). "L. plantarum decreased the levels of IL-1β, IL-6, TNF-α, and IFN-γ to enhance the immune barrier and effectively improve ulcerative colitis." (PMID 38540864, 2024). "In ulcerative colitis models, ALO reduces LTB4 and TNF‐α levels and inhibits myeloperoxidase activity and TNF‐α and IL‐1β mRNA expression." (PMID 38888378, 2024). "Existing study has shown that BA can significantly alleviate ulcerative colitis induced by 2,4,6-trinitrobenzene sulfonic acid (TNBS) by blocking the PI3K-AKT signaling pathway, thereby reducing the release of IL-6, TNF-α, and IL-1β." (PMID 39104394, 2024). "Olsalazine significantly increased the contents of IL-2, IL-10, IL-22, TGF and EGF in ulcerative colitis rats, and significantly decreased the scores of DAI, CMDI, HS and the contents in IL-7, IL-17, TNF-α, IL-1β and IFN-γ when compared with the model group." (PMID 37610966, 2023). "Inflammatory cytokines and mediators, such as IL-1b, IL-6, TNF-α, iNOS, and PGE2, are involved in inflammatory responses that induce ulcerative colitis in patients with intestinal inflammation." (PMID 37375714, 2023). "Inflammatory factors such as IL-1b, IL-6, TNF-α, iNOS, and COX-2, are frequently expressed in ulcerative colitis models." (PMID 37375714, 2023). "Oroxylin A as the main component extracted from Scutellariae radix can decrease the expression of inflammatory cytokines IL-6 and IL-1β, and attenuated IL-6/STAT3 signaling pathway in ulcerative colitis mice." (PMID 34997010, 2022). "The inflammatory response affects the formation of ulcerative colitis and increases the production of proinflammatory cytokines such as TNF-α, IL-1β, IL-6, and IFN-γ11,40." (PMID 35894303, 2022). "The expression of iNOS can be induced by endotoxins and proinflammatory cytokines (IL-1β and IFN-γ) during ulcerative colitis." (PMID 33995942, 2021).